SP1 (Sp1 transcription factor)
Diseases named in the same sentence as SP1 in open-access papers (continued):
Sharing a sentence is not in itself a finding about the gene and the disease.
hepatocellular carcinoma (continued). "We previously reported that HBx activated Lin28A/Lin28B through Sp1/c-Myc in hepatoma cells." (PMID 27050367, 2016). "In this study, we also showed that Sp1 was poly(ADP-ribosyl)ated by PARP-1 in hepatoma cells." (PMID 24367566, 2013). "Taken together, these data indicated that PARP-1 inhibition attenuated the poly(ADP-ribosyl)ation of Sp1 and significantly increased the expression of Sp1 target genes, resulting in G0/G1 cell cycle arrest and the decreased proliferative ability of the hepatoma cells." (PMID 24367566, 2013). "Another study by our group revealed a different mechanism of PTTG1 suppression by T3/TRs, showing that T3 stimulation in TR-expressing hepatoma cells inhibited expression of specificity protein 1 (Sp1), thereby suppressing PTTG1, a direct transcriptional target of Sp1." (PMID 23878812, 2013). "An interesting finding was that the majority of prostate cancers were unmethylated around a methylation hotspot (corresponding to the p-53, AP-2 and Sp-1/Sp3 binding sites), reported in both non-small cell lung carcinoma (61%) and hepatocellular carcinoma (33%)." (PMID 17453001, 2007). "PITPNM3, one of member of a large family of G protein-coupled receptors, promotes the development of different cancer, such as in hepatic carcinoma, mitofusin-2 could interact with transcription factor SP1 to suppress PITPNM3 expression, which contributed to the inhibition of tumor." (PMID 35609322, 2022). "It was also reported that miR-31-5p inhibited the proliferation, migration of HepG2 hepatocellular carcinoma (HCC) via targetting SP1." (PMID 29654167, 2018). "Therefore, we speculate that ZBP-89 and Sp1/Sp3 are involved in hepatocellular carcinoma (HCC) and Bak induction." (PMID 29653560, 2018). "Moreover, knockdown of Sp1 or PTTG1 inhibited proliferation of TR-expressing hepatoma cells." (PMID 23878812, 2013). "Startlingly, nuclear ANLN has been shown to form a transcriptional complex with SP1, thus enhancing KIF2C transcriptional activity and activating the mTORC1 pathway, which leads to the hepatocellular carcinoma bone metastasis." (PMID 41513610, 2026). "CAFs promote hepatocellular carcinoma malignancy by SERPINH1 secretion and regulating SENP3-mediated SP1/SQLE pathway." (PMID 40959099, 2025). "HNF4/Sp1 interactions that induce eosinophil RNase2 in cancer cells are also complex, where HNF-4/Sp1 and HNF-4/Sp3 activate the expression of human haem oxygenase-1 in hepatoma cells." (PMID 39858066, 2025). "Other studies have shown that Sp1, IRF1 and IRF2 can bind to the APOL1 promoter in hepatoma cells, and IRF1, IRF2 and STAT2 to the APOL1 promoter in podocytes and endothelial cells." (PMID 37924378, 2024). "Various trans-activating factors such as Sp1, c-Mybl2, NF-kB, and AP-1 participate in MAT2A transcriptional upregulation in hepatocellular carcinoma (HCC)." (PMID 39353892, 2024). "In gastric cancer, Sp1 regulates expression of leucine-rich repeat-containing receptor 5 (LGR5), a key stem cell factor, and in hepatocellular carcinoma, Sp1 induced LncRNA DPPA2 upstream binding RNA (DUBR)." (PMID 36982239, 2023). "Our results suggest that SP1 and NFY binding sites work as a single cis-element within the PNPT1 promoter, and that in hepatocellular cancer overexpressing PNPase, the promoter activity of PNPT1 depends on SP1 and/or NFY." (PMID 36232701, 2022). "circRNA circHipk2 expression in C2C12 myoblasts is mediated by Sp1, and circ-FOXP1 in hepatocellular carcinoma cells is regulated by SOX9." (PMID 35832649, 2022). "For example, SP1 overexpresses the long noncoding RNA TUG1, and promotes tumor growth in hepatocellular carcinoma." (PMID 34185412, 2021). "In hepatoma cells, expression of ADAMTS1 is regulated differentially by SP1 (specificity protein 1) and USF1 (upstream stimulatory factor 1) under normoxic and hypoxic conditions." (PMID 29212212, 2017).
hepatocellular carcinoma (continued). "In addition, we validated that Sp1 siRNA increased the sensitivity of HepG2-X and H7402-X cells to CDC using CDC analysis, whereas overexpression of C4BPα could abolish the increase, supporting that Sp1 is involved in the escape of hepatoma cells from complement attack induced by C4BPα." (PMID 27050367, 2016). "In some other conditions, VEGF expression and angiogenesis were independent of HIF-1α level, e.g. under hypoxic conditions,VEGF expression in hepatocellular carcinoma cells was HIF-1-independent, but was primarily controlled by the Akt/PI3K and SP1 pathways." (PMID 25823960, 2015). "Since both studies were performed in ovarian carcinoma and hepatocellular carcinoma, respectively, a cell type and/or tumor entity specific JNK-dependent regulation of Sp1 is highly probable." (PMID 26469969, 2015). "Sp1 can recruit HDAC4 to the promoter of miR-200a, resulting in silencing of miR-200a and promoting the proliferation and migration of hepatocellular carcinoma cells." (PMID 24830600, 2014). "In hepatocellular carcinoma cells, PARP-1 activation inhibits the SP1 signaling pathway to promote cell proliferation, whereas PARP-1 inhibition enhances SP1-mediated expression of checkpoint proteins (e.g., p21 and p27), leading to cell cycle arrest at the G0/G1 phase." (PMID 41304867, 2025). "SP1 is overexpressed in a number of cancer types and is considered as a poor prognosis factor, and NFY has been reported to be overexpressed in lung and hepatocellular cancer." (PMID 36232701, 2022). "In addition, the expression of SP1 (p < 0.001), the transcription factor controlling ectopic TIAM2S expression in hepatocellular carcinoma, is highly correlated with the TIAM2S protein in these CRC cell lines (r = 0.508, p < 0.05)." (PMID 32650570, 2020). "And this is consistent with previous study which reported that Sp1 shows a high expression in hepatocellular carcinoma versus paired nontumor liver tissues." (PMID 28466020, 2017). "In hepatoma cells, athough it seems that HBx-induced GATA3/2 activation and Ap-1 or SP-1 activation might results in opposite effect on MICA expression, we indeed observed that HBx suppresses MICA expression in our experiments." (PMID 27528231, 2016). "For example, in hepatocellular carcinoma (HCC), the deubiquitinase USP33 stabilizes Sp1, leading to increased c-Met expression and enhanced HCC metastasis." (PMID 40125551, 2025). "Moreover, the combination of the expression of SP1, NACO3, and TERT may serve as a survival predictor in hepatocellular carcinoma." (PMID 33239622, 2020). "MicroRNA-612 (miR-612) has been proven to suppress EMT, stemness, and tumor metastasis of hepatocellular carcinoma (HCC) via PI3K/AKT2 and Sp1/Nanog signaling." (PMID 32033570, 2020). "In liver cells or hepatoma cell lines (e.g., Huh-7 cells), TNFα and IL-1β induced by LPS only have minor effects on SOCS expression and their effects on GH resistance are mediated by reducing GHR gene transcription, probably through inhibition of Sp1/3 binding to GHR promoter." (PMID 32082258, 2020). "In conclusion, our study demonstrates that miR-324-5p suppresses hepatocellular carcinoma cell invasion by attenuate the expression and activity of MMP2 and MMP9, subsequently counteracting ECM degradation, through post-transcriptionally downregulating ETS1 and SP1." (PMID 26177288, 2015). "Furthermore, a study on hepatocellular carcinoma reported that ID decreased ENPEP expression and promoted angiogenesis and metastasis through the transcription factor SP1, providing additional insight into how ID may enhance hepatocellular carcinoma progression." (PMID 41190142, 2025). "They found that TERT depletion in hepatocellular carcinoma cells (HCC) resulted in reduced DNMT3B transcription, and they proposed that TERT itself may cooperate with the transcription factor Sp1 to promote DNMT3B transcription." (PMID 32297856, 2020).
hepatocellular carcinoma (continued). "Taken together, the effect of SCAMP1 on viral transcription is by the specific transcriptional inhibition of HBV EnhI/Xp, SP1, and SP2 promoters, rather than from a general or global effect on human hepatoma cells." (PMID 35216324, 2022). "Of note, previous studies have demonstrated that activation of Sp1 is unique for transcriptional regulation of DR5 without affecting DR4 expression in other cancer cells, including colon, hepatoma and ovarian cancer cells." (PMID 26320171, 2015).
glioma (106 papers, 1981 to 2026). A benign or malignant brain and spinal cord tumor that arises from glial cells (astrocytes, oligodendrocytes, ependymal cells). "The study found that oHSV-1 exhibited significant anticancer effects in vivo by suppressing the expression of Sp1 and invasion-associated genes, which are highly expressed in high-grade glioma tissue specimens." (PMID 37880659, 2023). "Further studies were performed, and we found that the enrichment of miR-21 in GA-MSCs exosomes was caused by the miR-21/SP1/DNMT1 positive feedback loop triggered by glioma exosomal CD44." (PMID 37481646, 2023). "In glioma samples, miR‐5188 expression was found to be an unfavourable factor and was positively associated with the mRNA levels of SP1 and c‐JUN, whereas negatively associated with the mRNA levels of FOXO1." (PMID 32902145, 2020). "Survival analysis results suggest that high expression of SP1 is associated with poor prognosis in glioma patients." (PMID 33327965, 2020). "In particular, the upregulation of DHEA in gliomas is caused by Sp1-mediated cytochrome P450 (CYP) 17A1 overexpression, implying that CYP17A1 is a potential target for glioma treatment." (PMID 31527549, 2019). "It has recently been documented that MGMT expression is associated with SP1 expression in glioma cell lines." (PMID 30583528, 2018). "As SP1 was identified as one of the downstream targets of miR-150-3p and aberrant expression of SP1 had been found to be associated with the development of cancer, we analyzed the expression level of SP1 in glioma tissues." (PMID 29654167, 2018). "Sp1 was detected to be over-expressed in many cancers, such as gastric, breast, pancreatic, glioma, and thyroid cancers, and is closely associated with the stage, invasive potential and metastasis." (PMID 29262634, 2017). "For example, loss of Sp1 in fibromyosarcomas, gliomas, multiple myeloma, lung, pancreatic and colon cancer cells, and rhabdomyosarcomas results in one or more of inhibition of growth, cell cycle progression, survival, migration and invasion." (PMID 26317792, 2015). "Moreover, the Kaplan–Meier survival analysis showed that high expression of SP1 is associated with poor prognosis in glioma patients." (PMID 33327965, 2020). "Applying TSProm to human brain, liver, and testis promoters, we identified clinically relevant transcription factors (TFs) in the brain, including SP1, MYC, and HES6, whose associations with gliomas and neuroblastomas highlight clinical relevance." (PMID 42244857, 2026). "The identification of SP1 as a central regulator in brain TSp-icity is particularly significant given its established role as a biomarker for glioma and neurodegeneration progression." (PMID 41279024, 2025). "Sp1 is overexpressed in a number of cancers, including breast, gastric, pancreatic, lung, brain (glioma), and thyroid cancers." (PMID 38540340, 2024). "Sp1 levels are found to be elevated in gliomas, which was reported to have an adverse relationship with patient survival in gliomas." (PMID 39795182, 2024). "And the study revealed a positive correlation between high expression levels of STAT3 and Sp1 and the clinicopathological grade of glioma." (PMID 39228402, 2024). "The lncRNA LINC01138 functions as an oncogenic driver; its silencing inhibits aerobic glycolysis via regulation of the microRNA-375/SP1 axis, thereby decreasing glioma cell proliferation." (PMID 39167430, 2024). "Deletion of SP1 has been shown to exhibit a 200-400-fold decrease in the basic promoter activity in glioma cells." (PMID 38521933, 2024). "Studies have proposed that Sp1 is an important transcription factor for the malignant progression of glioma." (PMID 36778118, 2023). "As TRIM56 has been revealed to promote radiotherapy tolerance in gliomas, our finding that SP1 drives TRIM56 transcription provides evidence for the mechanism through which SP1 promotes glioma radiotherapy resistance." (PMID 36870986, 2023).
glioma (continued). "In summary, we elucidated that GA-MSCs play a key role in promoting the formation of an immunosuppressive glioma microenvironment by amplifying glioma exosomal immunosuppressive signaling through the miR-21/SP1/DNMT1 positive feedback loop." (PMID 37481646, 2023). "One previous study reported increased CD133 expression levels in glioma-stem-like cells upon Sp1 overexpression that was suppressed by MitA." (PMID 36843002, 2023). "NLRP6 transcriptionally induced by SP1 affects the subsequent increase in NLRP6 inflammasome activation and further causes immune escape from CD8+ T cells and radiation resistance of glioma cells." (PMID 37723542, 2023). "There was an increased binding between Gαi2 promoter and Sp1 (specificity protein 1) transcription factor in glioma tissues and different glioma cells." (PMID 36778118, 2023). "Remarkably, Sp1 ChIP results revealed that Sp1-Gαi2 promoter binding 51 in various glioma cells (“P1-P3” primary cells and A172 cells) was substantially higher than it in Astrocytes1/2." (PMID 36778118, 2023). "Next, the lentiviral particles packaging Sp1-overexpressing construct were added to P1 glioma cells, and stable cells established (“oeSp1”)." (PMID 36778118, 2023). "SP1 has been reported to promote the malignant characteristics of glioma, including invasion, cancer stem cell enrichment, and treatment-resistance." (PMID 36870986, 2023). "miR-137 is a well-known suppressor of cell proliferation, mainly by regulating the cell cycle and enhancing differentiation of glioma stem cells via its downstream targets, such as Clcl12, Cox2, Pdgfr, Sp1, Tcf4 and/or Cdk6." (PMID 38138985, 2023). "Three candidate genes (RAF1, RB1, and SP1) were selected through KEGG pathway analysis, as all three genes were previously found to be associated with glioma pathogenesis." (PMID 36980172, 2023). "In primary glioma cells Gαi2 expression was significantly reduced following Sp1 silencing, KO or inhibition." (PMID 36778118, 2023). "Another study also revealed that miR-4310 induced by Sp1 targets PTEN to promote glioma progression." (PMID 35034634, 2022). "As the tight regulatory relationship between Sp1 and TIMP1 has been identified here, we aim at investigating both molecules simultaneously as a diagnostic signature in assessing the prognosis of glioma patients." (PMID 35778451, 2022). "In glioma, Sp1 is upregulated and enhances MMP-2-mediated cell invasion, which indicates a decreased survival." (PMID 35276059, 2022). "In summary, this study demonstrated that IR directly promotes the secretion of GDF15 from brain ECs and that GDF15 activates the VEGFA promoter in glioma cells through the p-MAPK1/SP1 pathway and consequently enhances angiogenesis in orthotopic brain tumors." (PMID 35280749, 2022). "In concordance, Sp1 is overexpressed in TMZ-resistant glioma cells, and inhibition of Sp1 restores the anticancer effects of TMZ50." (PMID 35778451, 2022). "It has been found that Sp1 is often highly expressed in most tumors, including gastric, pancreatic, lung, brain (glioma) and thyroid cancer 43–47." (PMID 35778451, 2022). "Some studies have shown that the molecular mechanism of glioma formation involved HDAC4-mediated SP1 and KLF5 deacetylation in selective MKK7 transcription and oncogenic JNK/c-Jun cascade activation." (PMID 35359455, 2022). "Our finding suggests a strategy for targeting TIMP1, which is short of an applicable drug in glioma patients, through inhibiting Sp1." (PMID 35778451, 2022). "The overexpression of transcription factor SP1 has been identified in diverse cancers, such as the brain (glioma), lung, pancreatic, and gastric." (PMID 35276059, 2022). "Both the RNA and protein levels of TIMP1 were decreased in response to Sp1 knockdown in glioma cells." (PMID 35778451, 2022). "In glioma, Sp1 promotes proliferation and invasion of glioma cells via upregulating oncogenes, such as ADAM17 and MDK48,49." (PMID 35778451, 2022).